MIR924HG (MIR924 host gene)
Synonyms: LINC00669
Gene: Long non-coding RNA gene on chromosome 18 (39,113,452 to 39,800,325, reverse strand). Ensembl gene ENSG00000267374.
Diseases named in the same sentence as MIR924HG in open-access papers:
MIR924HG is named in the same sentence as 5 diseases in open-access papers, as found by Europe PMC text mining. Sharing a sentence is not in itself a finding about the gene and the disease. The quoted sentences say what the papers report.
tumor (3 papers, 2020 to 2023). "We found that CDKN2B‐AS1, YEATS2‐AS1, MIR924HG, SLC16A1‐AS1, LRRC8C‐DT, and LINC01126 expression levels were significantly correlated with clinical stage and tumor grade in EC." (PMID 36525280, 2023).
cancer (2 papers, 2019 to 2021). A tumor composed of atypical neoplastic, often pleomorphic cells that invade other tissues. "Third, MIR924HG is expressed in a number of cancer cell lines, but consistently in samples representing iPS differentiation into neurons, according to the FANTOM5 miRNA promoter analysis." (PMID 30741946, 2019).
MIR924HG also shares sentences with these, for which no sentence is quoted: nasopharyngeal carcinoma (4 papers); lung adenocarcinoma (1); lung carcinoma (1).